STAT3 (signal transducer and activator of transcription 3)
Diseases named in the same sentence as STAT3 in open-access papers (continued):
Sharing a sentence is not in itself a finding about the gene and the disease.
breast cancer (continued). "Furthermore, Stat3 activation has been implicated as an important driver of brain metastasis in breast cancer, although the mechanisms are not fully understood." (PMID 25881542, 2015). "Furthermore, in human tumors, the highest STAT3 activity is found in CD44−/CD24+ breast cancer cells, markers associated with tumor-initiating capability, and EMT." (PMID 25699542, 2015). "Together these results suggest that trastuzumab resistance in PTEN deficient HER2+ breast cancer results in the EMT to transforms PTEN deficient HER2+ breast cancer to a triple negative phenotype that is dependent upon the IL-6/STAT3/NF-κB signaling axis for survival and self-renewal of CSCs." (PMID 26522776, 2015). "Further analysis with a ChIP assay confirmed that STAT3 could directly associate with the gene promoter for fascin in both breast cancer cell types." (PMID 24743777, 2014). "Our analysis of clinical breast cancers indicated that increased total STAT3 expression was associated with favourable outcome whether examined at the mRNA or protein level." (PMID 24728078, 2014). "STAT3 inhibition might therefore be a useful single agent or combination therapy in breast cancer while STAT1 inhibition may be more intimately associated with endocrine treatment failure and a useful therapeutic strategy to target resistance." (PMID 24728078, 2014). "To determine whether similar association of STAT3 phosphorylation was also present in primary human breast cancer samples, we examined the relationship between P-STAT3 (Y705) and ALDH1 protein expression in human breast cancer tissues using tissue microarrays." (PMID 24376586, 2013). "This signaling pathway involving NF-κB/IL-6/STAT3 has been demonstrated to be important in the pathogenesis of various epithelial cancers associated with inflammation, especially gastrointestinal cancer and breast cancer." (PMID 23705069, 2013). "SC-1 and SC-43 induced more potent apoptosis than sorafenib, in association with downregulation of p-STAT3 and its downstream proteins cyclin D1 and survivin in a dose-dependent manner in breast cancer cell lines (HCC-1937, MDA-MB-468, MDA-MB-231, MDA-MB-453, SK-BR3, MCF-7)." (PMID 23938089, 2013). "Our recent findings demonstrating that in the nucleus of breast cancer cells ErbB-2 is associated with Stat3 and PR, could help to explain the different sensitivity of both antibodies." (PMID 22356700, 2012). "As it is this inflammatory signature which is considered to be the cause of the increased risk of occurrence of breast cancer in the period immediately post-weaning 25–28, we suggest that epithelial Stat3 expression is at the very heart of the pathogenesis of pregnancy-associated breast cancer." (PMID 22081431, 2012). "For instance, in breast cancer (BC), hyperphosphorylation of STAT3 on the tyrosine residue Y705 has been linked to poor prognosis and increased metastatic potential." (PMID 41463071, 2025). "Various studies showed that expression of STAT5 by tumor cells could act as either a tumor suppressor or oncogene in breast cancer under different circumstances, while STAT3 expression in tumor cells has mainly been associated with a pro-tumoral microenvironment." (PMID 39703517, 2024). "Furthermore, pSTAT3 gene signatures were correlated with PD-L1 expression in tumor cells and immune cells of breast cancer patient tumors, and the activated forms of STAT3 and STAT1 were significantly associated with the expression of PD-L1 in breast cancer patients." (PMID 37830552, 2023). "Consistent with studies demonstrating that STAT3 is an early diagnostic tumor marker that is often constitutively overexpressed and activated in breast cancer, strategies aimed at modulating Ca2+ signaling in these tumors may be useful as a novel therapeutic approach." (PMID 37296835, 2023). "However, whether the overall survival of radiotherapy-treated patients with breast cancer is associated with L-6 and p-STAT3 levels requires further study." (PMID 36635302, 2023).
breast cancer (continued). "However, STAT3 was reported to be downregulated by IL-32θ, an IL-32 isoform, via direct interaction with PKCδ, resulting in a slowdown of the progression of macrophage-associated breast cancer." (PMID 37237509, 2023). "Luteolin- and silibinin-co-loaded with SDPN alleviated breast cancer metastasis in 4T1 tumor-bearing mice by regulating the conversion of tumor-associated M2 macrophages into the M1 phenotype and reducing the proportion of the M2-phenotype through co-action on STAT3 and HIF-1α." (PMID 37403048, 2023). "Overall, in this study we demonstrate that the cell-autonomous pro-metastatic functions of PD-L1 in breast cancer cells are fully dependent on all four N-linked glycosylation sites of the protein, and that N-linked glycosylation of PD-L1 at specific sites leads to STAT3 and STAT1 activation." (PMID 37830552, 2023). "Positive phospho-STAT3 (Y705) expression is highest in TNBC, followed by luminal A and luminal B, with HER2-enriched tumors showing the lowest rate of phospho-STAT3 immunostaining, suggesting that phospho-STAT3 may be a hallmark of more aggressive breast cancer subtypes." (PMID 35053592, 2022). "Although the exact mechanism for the increased levels of PD-1 and PD-L1 in BRCA1-deficient breast cancers remains elusive, we believe pSTAT3 might play an important role in this as a previous study has indicated that STAT3 activation could be responsible for the increased expression of PD-L146." (PMID 35304461, 2022). "In addition, S727‐phosphorylated mitochondrial STAT3 has also been implicated in breast cancer." (PMID 33605027, 2021). "Interestingly in breast cancer, autophagy inhibition is linked with constitutive STAT3 activity; this could be linked to nuclear accumulation of unphosphorylated STAT3." (PMID 32331320, 2020). "Thus, STAT3 could integrate between both distinct NF-κB signaling pathways, which coordinately mediates the inflammation-associated carcinogenesis in human breast carcinomas." (PMID 33396715, 2020). "However, elevated STAT3 expression was associated with better prognosis of breast cancer." (PMID 26959884, 2016). "Therefore, the observations in this study suggest that prophylactic therapy targeting STAT5 and STAT3 in high-risk women may also lower their breast cancer risk." (PMID 26146825, 2015). "Moreover, we identified STAT3 activation in a subset of patients with PTEN loss, suggesting that novel strategies to block the STAT3 pathway in combination with trastuzumab treatment may be especially relevant in PTEN- deleted breast cancer." (PMID 26234940, 2015). "Silencing GRN also reduced experiments because it induces robust stimulation of IL-6 and OSM-induced STAT3 transcriptional activity as STAT3 tyrosine phosphorylation and is physiologically measured by luciferase reporter assay, indicating that this relevant in breast cancer cell proliferation." (PMID 26000098, 2015). "Importantly, this conclusion is not restricted to transformed keratinocytes, as EGF-mediated Src, -MEK1, -ERK1/2 and -STAT3 phosphorylations were also severely impaired on KIAA1199 deficiency in breast cancer-derived MCF7 and SK-BR-3 cells, as well as in immortalized breast epithelial NMuMG cells." (PMID 25366117, 2014). "RHOT1 facilitates the EMT process, invasion, and metastasis of breast cancer cells by “sponge adsorbing” miR-106-5p, upregulating the expression of signal transducer and activator of transcription 3 (STAT3), and initiating the STAT3 signaling pathway." (PMID 41614928, 2026). "Elevated IL-6 levels correlate with poor prognosis in breast cancer patients and persistent IL-6/STAT3 activation promotes tumour proliferation, metastasis, angiogenesis and therapy resistance." (PMID 42316398, 2026). "BHLHE40-AS1, which lies antisense to the BHLHE40 promoter, functions independently of BHLHE40 and has been shown to modulate IL-6/STAT3 signaling in early-stage breast cancer, contributing to an immunosuppressive TME that promotes tumor progression." (PMID 41501810, 2026).
breast cancer (continued). "While hsa-miR-3184-5p has not yet been linked to endometriosis, it exerts tumor-suppressive effects in ovarian and breast cancers via modulation of XBP1/AKT/STAT3, FOXP4, and EMT-related signalling." (PMID 41501788, 2026). "We observed that STAT3 expression had the strongest positive correlation with KAT2A expression in metastatic breast cancer patients (R=0.74, p <0.001)." (PMID 41826695, 2026). "It suggests that the feedback activation of the STAT3 signaling pathway is a crucial reason for the insensitivity of TNBC to SAHA treatment compared to other breast cancer subtypes." (PMID 40091020, 2025). "The dysregulation of MALAT1 has been linked to poor prognosis in breast cancer, where its upregulation activates oncogenic pathways such as PI3K/AKT, Wnt/β‐catenin, and STAT3, leading to increased proliferation, survival, and therapeutic evasion." (PMID 41031251, 2025). "For instance, IL-6 plays a central role in inflammation, autoimmunity, cancer, and age-related pathologies, primarily via the IL-6/STAT3 signaling pathway, and elevated levels of TNF-α have been associated with breast cancer recurrence." (PMID 41155372, 2025). "For instance, the importance of STAT3 in promoting glycolysis through transcriptional regulation has been demonstrated in proliferating breast cancer cells." (PMID 41269404, 2025). "STAT3 has been shown to regulate SNHG3 expression in breast cancer cells, positioning it as a potential therapeutic target for inhibiting SNHG3." (PMID 41042421, 2025). "We demonstrate that the inhibition of the APE1 redox domain decreases STAT3 transcriptional activity in breast cancer." (PMID 41090323, 2025). "In breast cancer, luteolin suppresses the expression of cancer-promoting proteins (p-Akt, p-STAT3, and p-EGFR), reduces progestin-dependent VGF secretion and cell growth viability, and increases Bax expression." (PMID 40487864, 2025). "Beyond its classical role, leptin promotes cancer progression including angiogenesis and metastasis; by activating oncogenic pathways, such as the JAK2/STAT3 axis; in breast cancer." (PMID 41463012, 2025). "Leptin-activated STAT3 signaling is well known to promote the growth and progression of breast cancer." (PMID 41463012, 2025). "Systemically, breast cancers remodel liver metabolism via signal transducer and activator of transcription 3 (STAT3)-suppressor of cytokine signaling 3 (SOCS3)-AMPK to create metastatic niches." (PMID 40725147, 2025). "STAT3 is an oncogene, and its expression level is elevated in patients with breast cancer as well as head and neck squamous cell carcinoma." (PMID 40282476, 2025). "Statement of Retraction: Homeodomain-containing gene 10 contributed to breast cancer malignant behaviors by activating Interleukin-6/Janus kinase 2/Signal transducer and activator of transcription 3 pathway." (PMID 40267127, 2025). "The IL6/JAK/STAT3 signaling pathway is a classical pathway that influences the onset and progression of breast cancer." (PMID 40841364, 2025). "The IL-10/STAT3/Bcl-2 axis plays a pivotal role in mediating TAM-induced breast cancer cell survival and paclitaxel resistance." (PMID 40909271, 2025). "In breast cancer, direct STAT3 signaling is shown to increase the levels of survivin, which is important to maintain hypoxic states in the TME." (PMID 41376623, 2025). "To identify the regulatory role of RSL3 on STAT3 expression, we treated PARPi-resistant breast cancer cells with a serial dose of RSL3." (PMID 41463402, 2025). "Additionally, JAK2/STAT3 activation has been linked to enhanced migration and invasion of breast cancer (BC) cells (Pathway D)." (PMID 40277814, 2025). "Research shows lactate secreted by tumors promotes breast cancer growth via M2 macrophage polarization through extracellular signal-regulated kinases (ERK)/STAT3 pathway induction." (PMID 40420174, 2025).
breast cancer (continued). "Studies in tumors have mainly focused on their targeted inhibitory effect on the STAT3 signaling pathway, inhibiting STAT3 phosphorylation, DNA‐binding activity, and transcriptional activation to induce apoptosis in pancreatic cancer and breast cancer cells." (PMID 41438489, 2025). "Here, we investigated the role of APE1 redox activity in the transcriptional activity of STAT3 and their crosstalk on proliferation, migration, and invasion processes in breast cancer cells." (PMID 41090323, 2025). "Emerging evidence highlights the critical role of STAT3 signaling in mediating CDK4/6 inhibitors resistance in several cancers including breast cancer." (PMID 40303916, 2025). "In vitro experiments revealed that SNHG3 expression significantly decreased when STAT3 was knocked down and increased when STAT3 was overexpressed in breast cancer cells." (PMID 41042421, 2025). "Considering these findings, the inhibitory effect of chalcone-9 on the JAK-STAT pathway, including STAT3, implies that chalcone-9 is a very prospective breast cancer treatment." (PMID 40199813, 2025). "Previous studies have also found that STAT3 promoted the transcription of FTO in breast cancer cells." (PMID 40712780, 2025). "Another small molecule, STATTIC, specifically disrupts STAT3 dimerization and DNA binding while also inhibiting enzymes responsible for STAT3 activation, leading to apoptosis in breast cancer cells." (PMID 40166646, 2025). "Using LIMMA, 779 differentially expressed genes (DEGs) related to breast cancer stem cells were identified, highlighting the roles of STAT3 and p65 in tumorigenesis and requiring further exploration." (PMID 40081286, 2025). "One such compound, STA‐21, a naturally occurring deoxytetrangomycin, selectively binds to the SH2 domain, preventing STAT3 dimerization and nuclear translocation, thereby significantly reducing the proliferation and progression of breast cancer cells." (PMID 40166646, 2025). "ANGPTL4 has been shown to promote the pro-tumorigenic effect of CAFs in a murine model of breast cancer by inducing STAT3, a transcription factor known for its role in EMT, angiogenesis, and inhibiting apoptosis." (PMID 40233044, 2025). "In conclusion, leptin was found to upregulate MTA1 expression via the Ob-R/STAT3 signaling pathway, which in turn promotes VM by regulating the expression of VM-related proteins in breast cancer cells." (PMID 40565190, 2025). "We predicted that BO treats breast cancer through STAT3 using network pharmacology, molecular docking, and molecular dynamics simulations, and we validated the predictions using Western blotting." (PMID 40076902, 2025). "These signaling pathways and targets are likely key mechanisms through which BO treats breast cancer, including pathways, such as those of STAT3, NFKB1, PI3K-Akt, PD-L1 expression, and the PD-1 checkpoint." (PMID 40076902, 2025). "Among emerging candidates, STAT3 has emerged as a critical regulator in breast cancer progression, particularly in triple-negative subtypes, demonstrating strong prognostic value and immunotherapy response associations." (PMID 40636126, 2025). "In this study, we aimed to investigate the involvement of cytoplasmic HMGB1 in the STAT3 signaling and expression of PD-L1 in breast cancer." (PMID 40389855, 2025). "In this investigation, we demonstrated through in vitro screening, network pharmacology, molecular docking, and experimental validation that BO exerts its therapeutic effects on breast cancer via STAT3." (PMID 40076902, 2025). "The feedback loop further enhances IL-6 expression via activated STAT3, rendering IL-6 less effective in breast cancer cells with low STAT3 expression." (PMID 40909271, 2025). "To this end, we induced DNA damage in our set of RBM14- vs. luciferase-overexpressing lung and breast cancer cell lines and treated with the STAT3 inhibitors C188-9 and HJC052 for 72 h." (PMID 39870664, 2025).
breast cancer (continued). "Napabucasin (BBI608) is a small-molecule STAT3 inhibitor that has been shown to reduce breast cancer and glioblastoma progression by mediating STAT3 signaling." (PMID 40075607, 2025). "In breast cancer, STAT3 functions as a transcription factor that regulates gene expression of several direct target genes involved in proliferation, migration, EMT, and chemoresistance." (PMID 40507264, 2025). "Inhibition of JAK/STAT3 signaling suppresses self-renewal of breast cancer stem cells (BCSCs) and downregulates key lipid metabolic genes such as carnitine palmitoyltransferase 1B (CPT1B), which encodes a rate-limiting enzyme in fatty acid β-oxidation (FAO)." (PMID 41269404, 2025). "By dysregulating downstream targets involved in cell proliferation, angiogenesis, and other critical biological processes, hyperactivated STAT3 contributes to the initiation and progression of breast cancer." (PMID 40949156, 2025). "Homeodomain-containing gene 10 contributed to breast cancer malignant behaviors by activating Interleukin-6/Janus kinase 2/Signal transducer and activator of transcription 3 pathway." (PMID 40267127, 2025). "Other group has concluded AGN induces caspase-dependent apoptosis by inhibiting signal transducer and activator of transcription 3 signaling in HER2-overexpressiong SKBR3 breast cancer cells." (PMID 40452850, 2025). "For example, IL-6 is highly expressed in this microenvironment and can activate the STAT3 pathway through paracrine and autocrine pathways, thereby promoting breast cancer cell proliferation." (PMID 40860340, 2025). "Contrary to previous reports of STAT3 upregulation in breast cancer, our integrated TCGA/GTEx analysis demonstrated higher constitutive expression in normal tissues, with survival analysis showing no significant prognostic impact of mRNA levels alone." (PMID 40636126, 2025). "This study focuses on STAT3 to elucidate its tumor-intrinsic mechanisms and explore its potential as a multifaceted therapeutic target in breast cancer." (PMID 40636126, 2025). "Particularly, TAMs induce STAT3 pathway regulating the expression of stemness genes, via NF-kappa-B activation, in CSCs in different malignancies including breast cancer, liver cancer, prostate cancer, pancreatic cancer and colon cancer." (PMID 39981232, 2025). "In breast cancer, melatonin treatment reduces STAT3 phosphorylation, thereby inhibiting epithelial mesenchymal transformation and metastasis." (PMID 40756978, 2025). "The results collectively demonstrate that STAT3 is essential to the regulating SNHG3 expression in breast cancer cells." (PMID 41042421, 2025). "In xenograft models of breast cancer, curcumin reduced tumor volume by modulating STAT3 signaling, increasing apoptotic markers (cleaved PARP, caspase-3, -7, -9, Bax, Bid) and decreasing antiapoptotic proteins (Bcl-2, Mcl-1, Bcl-xL)." (PMID 41020838, 2025). "The leptin/Ob-R/STAT3 signaling axis plays a critical role in breast cancer development by regulating target genes involved in tumor growth and progression." (PMID 40565190, 2025). "TAM-derived IL-6 plays a crucial role in TAM-mediated cancer stem cell enrichment by activating STAT-3 signalling and influencing breast cancer cell migration and angiogenesis; however, its expression was relatively low across all groups." (PMID 40547518, 2025). "The decrease in glycolysis observed in genistein-treated tamoxifen-resistant (TAM-R) breast cancer cells is likely linked to important changes in HK2 and STAT3 expression." (PMID 39859445, 2025). "Mounting evidence suggests that the JAK/STAT3 signaling pathway plays a key role in tumor metastasis and EMT, with an active IL6/JAK2/STAT3 axis and stem cell‐like characteristics contributing to the poor prognosis of metastasized breast cancers." (PMID 40874680, 2025). "STAT3 has been shown to interact with many different proteins in breast cancer to drive tumorigenesis." (PMID 40507264, 2025).